ABCA1 (ATP binding cassette subfamily A member 1)
Diseases named in the same sentence as ABCA1 in open-access papers (continued):
Sharing a sentence is not in itself a finding about the gene and the disease.
atherosclerosis (continued). "It was also suggested that the genetic polymorphisms of ABCA1 C69T gene could modulate the ABCA1 transcription, resulting in reduced HDL levels with an accumulation of cholesterol in the peripheral tissues, which leads to atherosclerosis and dyslipidemia-related disorders." (PMID 36553543, 2022). "Furthermore, Wang and colleagues demonstrated that LPS/ATP activation of NLRP3 inflammasome stimulates HMGB-1 release leading to cholesterol accumulation in VSMCs and foam cells formation during atherosclerosis, through the downregulation of LXRa and ABCA1 expression." (PMID 36244983, 2022). "Therefore, it is possible that genetic manipulation of ABCA1/ABCG1 in certain cells or tissues at different stages of life may influence atherogenesis or atherosclerosis progression differently." (PMID 35625607, 2022). "Atherosclerosis is a slowly progressing disease that takes many years to develop, even in patients with severe cholesterol homeostasis disorders such as Tangier disease (ABCA1 loss of function), who have no or very little HDL." (PMID 35464770, 2022). "Thus, ABCA1 is an important participant in the lipid-transport function of cells, due to which the transporter is involved in the regulation of inflammation, which is of great importance in the prevention of atherosclerosis." (PMID 36363591, 2022). "But in the course of atherosclerosis, the excessive lipid accumulation in macrophages induces the expression of uptake receptors such as scavenger receptors (SRs) but downregulates the expression of efflux transporters like ATP-binding cassette A1 and G1 (ABCA1 and ABCG1)." (PMID 35498045, 2022). "Furthermore, plasma exosomal miR-30e and miR-92a expressions were up-regulated in atherosclerosis and negatively correlated with plasma cholesterol and ABCA1 levels, providing a new biomarker for the clinical diagnosis and treatment of coronary atherosclerosis." (PMID 33664877, 2021). "A significant increase in ABCA1 mRNA levels in macrophages and plaques is accompanied by a decrease in the ABCA1 level, which is considered a result of the post-translational regulation of protease degradation and may play a role in the development of atherosclerosis due to RCT impairment." (PMID 34940525, 2021). "ABCA1 is involved in the formation of HDL particles by promoting cholesterol transfer from the cells to apolipoprotein A. Reduction in ABCA1 expression, especially in macrophages, may promote atherosclerosis and cholesterol deposition in peripheral tissues and organs." (PMID 33531564, 2021). "In addition, transgenic mice overexpressing ABCA1 showed a low incidence of atherosclerosis." (PMID 34445501, 2021). "Other targets and signaling pathways that may be regulated by miR-30d-3p and miR-140-3p were also predicted and analyzed to provide a basis for further studies on the regulation of circRNA KHDRBS1 and circRNA ABCA1 in vascular endothelial injury and atherosclerosis." (PMID 34307490, 2021). "Thus, CXCL8 may influence the development of atherosclerosis via the inhibition of cholesterol efflux protein ABCA1 thereby promoting the development of foam cells." (PMID 33503867, 2021). "In addition, ANXA1 may increase ABCA1 expression, but the effect on atherosclerosis development is unknown." (PMID 32894039, 2020). "The association between altered HDL concentrations and many other ABCA1 variants, including R219K (rs2230806) is well established by previous studies, which are linked to the development of ischemic heart disease (IHD) by the increasing risk of atherosclerosis in the general population." (PMID 33066695, 2020). "Hence, co-administration of rHDL and LXR agonist could serve as a synergetic treatment for atherosclerosis by addressing both ABCA1/G1 expression and cholesterol acceptor levels." (PMID 33390931, 2020). "GLRX, RNF13, and ABCA1 might be potential targets for atherosclerosis treatment." (PMID 33240650, 2020).
atherosclerosis (continued). "In addition, butyrate could improve atherosclerosis through the upregulation of ABCA1 expression and cholesterol efflux in macrophages through the Sp1 pathway." (PMID 33312718, 2020). "The miR-143/145 can target ATP-binding cassette transporter 1 (ABCA1), whereas the miR-92a can target Kruppel-like transcription factor that modulates shear stress genes, conferring other protective effects on physiology of blood vessels during atherosclerosis." (PMID 32937836, 2020). "Also, the downregulated TCF21 expression induced by CXCL12 could decrease the promoter activity of ABCA1 and ABCA1 expression, thus inhibiting ABCA1-dependent cholesterol efflux from macrophages and promoting atherosclerosis." (PMID 32582717, 2020). "As a vital defense process against the development of atherosclerosis, reverse cholesterol transport contains some steps and the first one is the lipid efflux from cells within the arterial wall, which is modulated by membrane transporters including ABCA1 and ABCG1." (PMID 31379468, 2019). "Thus, ABCA1 might act as a target for the prevention and treatment of atherosclerosis not only for its effects on cholesterol accumulation but also for its roles in the inflammatory response." (PMID 30647536, 2018). "Therefore, by modulating LXR-driven ABCA1 gene expression through the SHC1/PI3K/AKT/PPARγ/LXRα axis, LRP1 is presenting itself as a pivotal regulator of the metabolic as well as inflammatory processes underlying atherosclerosis." (PMID 29144234, 2017). "Therefore, targeted inhibition of ABCA1 DNA methylation, if achievable, could provide a new therapeutic approach to combating atherosclerosis and cardiovascular diseases." (PMID 27295295, 2016). "Thus, ABCA1 has been considered a potential target in the treatment of atherosclerosis." (PMID 27136542, 2016). "Thus, by activating ABCA1, it is possible to inhibit the progression of premature atherosclerosis." (PMID 25478513, 2013). "Thus, downregulation of CD36 and upregulation of ABCA1 in macrophages may have contributed to the slower progression of atherosclerosis in the brachiocephalic artery of AdipoR2-/-ApoE-/- mice in the present study." (PMID 24324556, 2013). "Despite the decreased serum lipid levels in ABCA1 KO and ABCA1/ABCA7 dKO transplanted mice, significantly higher amounts of foam cells were observed in the peritoneal cavity of these animals compared to controls, while also the susceptibility to atherosclerosis was increased." (PMID 22403608, 2012). "Interestingly, dKO transplanted mice, thus, showed a less severe increase in both foam cells and atherosclerotic lesion size compared with ABCA1 KO transplanted mice, indicating that ABCA7 deletion attenuates the effect of ABCA1 deletion on foam cell formation and atherosclerosis." (PMID 22403608, 2012). "Thus, the capacity of methotrexate to reduce the onset of atherosclerosis may be partially attributed to the adenosine-driven upregulation of ABCA1 and 27-hydroxylase which expedites cholesterol efflux." (PMID 21490773, 2011). "Mutations in ABCA1 have been shown to cause Tangier-disease, a rare autosomal recessive disease which is characterized by extremely low plasma HDL-concentrations, the accumulation of foam cells in various tissues and moderately increased atherosclerosis suceptibilty." (PMID 19348677, 2009). "Because ABCA1 plays an important role in lipid transport, impaired expression of ABCA1 in the aorta could potentially be responsible for the increased total cholesterol and the enhanced sensitivity to atherosclerosis in the smLRP1−/− mice." (PMID 19718435, 2009).
atherosclerosis (continued). "As expected, cholesterol transporters, ABCA1 and ABCG1, are also important targets through which foamy macrophages influence atherosclerosis progression." (PMID 40384967, 2025). "Taken together, the downstream genes of ARL4C, including ABCA1, ALDH1A3, ARF6, ENHO, FLNA, LRP6, OSBPL5, Snail2, and SOX2 play an important role in atherosclerosis." (PMID 40176913, 2025). "A recent study highlighted a compelling interplay among T-cadherin, miR-101-3p, ATP-binding cassette transporter A1 (ABCA1), and C1q/TNF-related protein 15 (CTRP15) in atherosclerosis progression." (PMID 40649905, 2025). "In this study, based on the atherosclerosis apoE−/− mice model induced by an HFD, we further verified the effect of CGE on the PPAR-γ-LXR-α-ABCA1 signaling pathway." (PMID 41464973, 2025). "Red watermelon has potential in atherosclerosis prevention by modulating the expression of PCSK9, LOX-1, CD36, ROS, TNFα, and ABCA1." (PMID 40699832, 2025). "The impaired molecular machinery we observed—including reduced expression of receptors (Scarb1) and transporters (Abca1, Abcg1)—strongly suggests a functional deficit in the lymphatic RCT pathway in advanced atherosclerosis." (PMID 41465071, 2025). "Capsaicin promotes cholesterol efflux via upregulation of the expression of ABCA1 and ABCG1 in macrophages of atherosclerosis." (PMID 39809738, 2025). "The genes for ABC transporters ABCA1 and ABCG1 are LXR targets and ABCA1 and ABCG1 strongly influence atherosclerosis both LXR-dependently and LXR-independently." (PMID 40305368, 2025). "ABCA1 and ABCG1 transporters are potential pharmacological targets for the prevention and treatment of atherosclerosis." (PMID 41300518, 2025). "The atherosclerosis control group (K+) exhibited significantly elevated PCSK9 and foam cell formation, alongside suppressed ABCA1 expression, indicating enhanced atherosclerotic progression." (PMID 40699832, 2025). "It is known that lipid transport proteins (CAV-1, ABCA1, SREBP-1, LXR, etc.)and inflammation (HMGB1, CXCL13, TIMP-1, etc.)in blood vessels mediate the formation of atherosclerosis." (PMID 38622667, 2024). "Together, our data demonstrate that LXN ablation upregulates the expression of ABCA1 and ABCG1 in macrophages in vitro or atherosclerosis in vivo." (PMID 39424784, 2024). "Research suggests that diminished functions of ABCA1 and ABCG1 result in cholesterol accumulation within cells and contribute to atherosclerosis development." (PMID 38474781, 2024). "ARL4C also plays a role in drug targeting; miR-26 promotes foam cell formation by reducing ABCA1 and ARL4C expression, supporting the development of drugs targeting atherosclerosis." (PMID 39268462, 2024). "The expression of transporters responsible for cholesterol efflux (LXRa, LXRb, and ABC transporters ABCA1 and ABCG1) prevents the progression of atherosclerosis and stabilizes the plaques." (PMID 38673936, 2024). "In this regard, ATP-binding cassette transporters (such as ABCA1 and ABCG1) mediate cholesterol efflux from macrophages, thus limiting the formation of foam cell and atherosclerosis." (PMID 39424784, 2024). "TUG1 is extensively linked with several cholesterol efflux genes, including apolipoprotein M (ApoM), ABCA1, and ABCG1, and consequently with atherosclerosis." (PMID 39273193, 2024). "The cholesterol transporters ABCA1 and ABCG1 are recognized for their protective role against atherosclerosis." (PMID 39524227, 2024). "Our group’s study showed that in macrophages, IFN-γ downregulates the expression of ABCA1 by activating the JAK/STAT1 signaling pathway, thereby promoting the development of atherosclerosis." (PMID 37670950, 2023).
atherosclerosis (continued). "It has been validated that the specific overexpression of miR-33 generates a decrease in the translation of ABCA1 and ABCG1 transporters, which leads to the development and/or progression of atherosclerosis." (PMID 37754229, 2023). "miR-33a deficiency or inhibition in mice has been shown to increase cellular cholesterol export through up-regulation of ABCA1, thereby elevating blood high-density lipoprotein cholesterol (HDL-C) levels and inhibiting atherosclerosis." (PMID 37263777, 2023). "Collectively, these results suggest that AG ameliorates atherosclerosis via inhibiting inflammation and improving cholesterol efflux by inhibiting the TLR4/NF-κB pathway by up-regulating ABCA1 and ABCG1." (PMID 37920216, 2023). "Upregulation of ABCA1 and ABCG1 expression can inhibit macrophage-derived foam cell formation and thereby effectively reduce the onset and progression of atherosclerosis." (PMID 36923537, 2023). "Binding of ligand to LXRα results in the upregulation of ABCA1 and ABCG1 transcription in macrophages, enhancement of cholesterol efflux, and inhibition of atherosclerosis progression." (PMID 36713845, 2023). "LXR agonists promote reverse cholesterol transport via ABCA1 and ABCG1, protecting against atherosclerosis." (PMID 36768382, 2023). "Previous studies have shown that another polysaccharide from brown algae, fucoidan, inhibits atherosclerosis by regulating the expression of genes involved in cholesterol reverse transport (RCT), such as ABCA1, SR-A1, and PPAR." (PMID 38132943, 2023). "We demonstrate that SFN can play a preventive role in macrophage foam cell formation and atherosclerosis through restraining cholesterol uptake and inducing efflux via the potential modulation of the expression of CD36, ABCA1/G1, PPARγ and Nrf2/HO-1." (PMID 37432260, 2023). "One possible explanation is that aerobic exercise increases the expression of ATP-binding cassette transporter A1 (ABCA1) and ApoAI, inhibiting atherosclerosis." (PMID 37398909, 2023). "Targeting ABCA1, ABCG1, and SR-BI to promote cholesterol efflux represents a potential strategy to inhibit foam cell formation and atherosclerosis." (PMID 36768748, 2023). "At the same time, it promotes the expression of ABCA1 and SR-BI in both lysophosphatidic acid (LPA)-induced macrophages and HFD-fed ApoE−/− mice, leading to attenuated foam cell formation and atherosclerosis." (PMID 36768748, 2023). "In macrophages, GDF-15 induces the expression of ABCA1 by triggering the PI3-K related pathway, and then indirectly results in atherosclerosis." (PMID 35842724, 2022). "The regulation of the functional activity of ABCA1 and ABCG1 and their disorders are also of clinical interest and are a promising target for the treatment of atherosclerosis." (PMID 36363640, 2022). "Since these subsets have both pro- and anti-inflammatory effects, and the loss of Abca1/Abcg1 in T cells does not affect a single predominant T cell subset, this effect on atherosclerosis could be due to counter-regulatory inflammatory effects in the aorta during sterile inflammation." (PMID 35778407, 2022). "ABCA1 plays a crucial role in HDL-C production and cholesterol efflux thereby protecting against atherosclerosis." (PMID 35743794, 2022). "Reduced lipid-exporting function of ABCA1 and ABCG1 in vascular wall macrophages is one of the key links to foam cell formation and progression of atherosclerosis." (PMID 35897703, 2022).
atherosclerosis (continued). "LXR also plays an important role in RCT by regulating several transporters including ABCA1 and ABCG1, so can help to reduce cholesterol and atherosclerosis." (PMID 36159325, 2022). "In contrast, the inhibition of HDAC3 in bone marrow-derived macrophages found in mice raises the levels of ATP-binding cassette transporter A1 (ABCA1), which is involved in atherosclerosis prevention." (PMID 35656103, 2022). "Quercetin prevents the development of atherosclerosis in ApoE−/− mice by regulating the expression of PCSK9, CD36, PPARγ, LXRα, and ABCA1." (PMID 35845584, 2022). "Acetylation of PPARγ at K268/K293 increases atherosclerosis through upregulating ABCA1, ABCG1, and NcoR but inhibiting PRDM16, while deacetylation of PPARγ at K268 and K293 alleviates atherosclerosis." (PMID 35309069, 2022). "Induction of the endothelial expression of both ABCA1 and ABCG1 by an agonist of the nuclear receptor liver X receptor (LXR) also correlates with reduced atherosclerosis in mice." (PMID 35464770, 2022). "Furthermore, HIF-1 is also known to regulate key factors relevant to atherosclerosis, such as genes involved in apoptosis, nitric oxide pathway, inflammation, and intracellular redox homeostasis and lipid metabolism, including ATP binding cassette subfamily A member 1 (ABCA1)." (PMID 36407436, 2022). "Several studies have reported that activation of LXRs inhibit the development of atherosclerosis, a property attributed to LXR-mediated ABCA1 expression and cholesterol efflux in macrophages." (PMID 35219337, 2022). "For instance, Cav-1 absence in aortic endothelial inhibits atherosclerosis by attenuating LDL transcytosis and enhancing autophagic flux, while in macrophages Cav-1 promotes THP-1 differentiation, ABCA1 expression and cholesterol efflux." (PMID 36407436, 2022). "To understand the mechanistic role of myeloid Jak2 in atherosclerosis, we treated BMDM with an LXR agonist, TO91317 that increases the transcription of ABCA1 and ABCG139–41." (PMID 35169231, 2022). "In atherosclerosis, kcnq1ot1 enhances HDAC3 expression by competitively binding to miR-452-3p, thereby inhibiting ABCA1 expression as well as cholesterol efflux." (PMID 35806493, 2022). "Previous studies have demonstrated a crucial role for PPARγ in the induction of ABCA1/ ABCG1 expression, and the prevention of foam cell formation and atherosclerosis progression." (PMID 35590369, 2022). "ABCA1, ABCG1, and scavenger receptor class B type 1 (SRB1) promote cholesterol efflux and exchange of cholesterol to influence atherosclerosis in mice." (PMID 34095317, 2021). "Considering lncRNA GAS5 as a target for the treatment of atherosclerosis in humans, it can be seen that GAS5 has proatherogenic properties, promoting methylation of the ABCA1 promoter region." (PMID 34940525, 2021). "Research on Tangier disease and ABCA1 has had a tremendous impact on the understanding of HDL cholesterol metabolism and atherosclerosis." (PMID 34831381, 2021). "The data on the participation of ABCA1 in platelet function and ensuring adequate hemostasis are interesting, considering the significance of hemostatic disorders in COPD and atherosclerosis." (PMID 34201488, 2021). "Here we review the available data on the expression of ABCA1, ABCG1 and SR-B1 in patients with atherosclerosis, CVD, and animal models of atherosclerosis." (PMID 34940525, 2021). "ABCA1 and CPT1 were previously demonstrated to alleviate atherosclerosis or diabetes by regulating the NF-κB signaling pathway." (PMID 34789275, 2021). "LncRNA TUG1, which is associated with the development of atherosclerosis, reduces the expression of not only ABCA1 but also ABCG1 at the RNA and protein levels, which probably decreases RCT effectiveness and atherosclerosis progression." (PMID 34940525, 2021).